CD4 (CD4 molecule)
Diseases named in the same sentence as CD4 in open-access papers (continued):
Sharing a sentence is not in itself a finding about the gene and the disease.
infection (continued). "Twenty four hours following infection, autologous CD4+ T-cells were added at a 1:1 ratio, cultured for an additional 4 hours, fixed, and stained as described in the Materials and Methods." (PMID 27930745, 2016). "All GFP-expressing CD4+ T cells in the spleen and liver during secondary infection coexpressed YFP, showing that IFN-γ+CD4+ T cells were also the dominant source of IL-10 during secondary infection." (PMID 27630165, 2016). "While CCR2 and CCR5 were only increased in the CD4+ TEM cell subset after infection, expression of CXCR6 and CD11c was much more abundant in CD8+ TEM cells." (PMID 27272720, 2016). "We identified that IL-27, which was produced by myeloid cells during the initial days of infection, promoted the generation of IL-10+CD4+ T cells in the spleen." (PMID 27926930, 2016). "CD4+ T cells constituted the dominant source of IL-10 (typically >50% of the total IL-10 response) in all examined organs throughout the course of infection, with the notable exceptions of the spleen (day 14 p.i. or later) and the blood (day 4 p.i.)." (PMID 26459508, 2016). "In order to assess the mode of action of the mRNA based rabies vaccine, we addressed the role of mRNA vaccine-induced CD4+ T cells in forming VN antibodies and in protecting against challenge infection." (PMID 27336830, 2016). "Mirroring the vaccine enhanced vvG/RSV model, we observed an increased influx of CD4+ T cells in the lungs and airways in AvCystatin treated mice undergoing primary infection." (PMID 27560829, 2016). "While comparable frequencies of pulmonary CD4+ T cells were present between the two strains at 90 days post-infection, the frequencies of pulmonary CD4+CD44+ T cells were reduced in p55∆NS mice." (PMID 27995986, 2016). "In fact, plasma viral load and CD4+ T cell counts declined throughout the infection, accompanied with increased ANXA1 expression in PBMCs and in the gut." (PMID 27484833, 2016). "In fact, while % of naive CD4+ T cells (CD62L+CD44low) showed a significant reduction at all time points after infection, % of memory CD4+ T cells (CD44highIL-7Rα+) remained unchanged when compared to naive mice." (PMID 27905502, 2016). "In consideration of these studies, we posited that CD4+ T cells similarly control ivag challenge infection with oculogenital C. trachomatis serovars." (PMID 27606424, 2016). "RV infected w/t mice displayed an increase in the number of CD3+CD4+ T cells expressing Tbet compared to phosphate buffered saline (PBS) challenged w/t animals on day 7 post-infection." (PMID 27683080, 2016). "Taken together, these data indicated that ICOS-signalling promoted CD4+ T-cell dependent humoral immune responses and parasite control during Py17XNL-infection." (PMID 27812214, 2016). "This leads to NFAT translocation and accumulation within the nucleus and was required for productive infection of unstimulated primary CD4+ T cells." (PMID 27383627, 2016). "Smaller activation barriers and more-favorable free energy differences between state 1 and state 2 should allow a higher occupancy of Env protomers by CD4, lowering CD4 requirements for productive infection." (PMID 27795397, 2016). "CD4+ T cells were cultured in IL-2+ Ritonavir for single round infection, or additionally stimulated with PHA which resulted in a strong induction of activation measured by CD25 and CD69." (PMID 27383627, 2016). "The frequencyof IL-10 and IFN-γ double producers within CD4+ Tcells also increased 7 days upon infection in all tissues analysed, except OAT,and was still detected increased in GAT and MAT by 21 days (Figs5e and 6e)." (PMID 27001522, 2016). "At the infection site, few parasites remain viable thanks to the presence of CD4+ CD25+ regulatory T cells that produce IL10." (PMID 26969511, 2016). "Next, we examined the role of PD-1 in CD4+ CD62Llo effector memory T cell responses, 5 days following homologous re-infection." (PMID 27217330, 2016).
infection (continued). "As for cell-free virus spread, however, productive infection of target cells by cell-to-cell transmission requires the assembly of virus particles competent for the fusion process and the expression of CD4 and co-receptors on the target cell." (PMID 27489023, 2016). "In the acute phase of infection, there is prolific viral replication with broad viral distribution to lymphoid organs and many immune cell subsets including CD4+ T cells, CD8+ T cells, B-cells and monocytes/macrophages." (PMID 29056720, 2016). "Although CD4+YFP+ T cells were also the major source of IL-10 in the spleen during the early stages of primary infection, the numbers of splenic CD4+YFP+GFP+ T cells were significantly lower during primary infection than during secondary infection." (PMID 27630165, 2016). "The role of CCL2 in inducing Th1 protective immunity and fungal clearance during C. neoformans infection has been demonstrated by its involvement in recruiting macrophages, CD4+ T cells, and NK T cells to the site of infection." (PMID 27165801, 2016). "This allows the cells to respond faster when they encounter their cognate antigen at sites of infection and be easily polarized into CD4 helper T cell subsets depending upon the cytokine milieu they encounter." (PMID 27280403, 2016). "IFNAR1-signalling hindered the resolution of infection, and acted early via conventional dendritic cells to restrict CD4+ T-cell activation and their interactions with B-cells." (PMID 27812214, 2016). "We found clear evidence of CD4+ T cell exhaustion in our model, paralleling results from both acute mouse models and human infection." (PMID 27583554, 2016). "Median CD4 + T cell counts in the first follow-up (<3 months after infection confirmation) was 360.9 (IQR: 238.3–499.0) cells/μl." (PMID 27698457, 2016). "Accordingly, we measured the expression of Ki67 and Bcl2 by flow cytometry within CD38+ and CD38- CD4+ T cells circulating in the healthy volunteers prior to infection, as well as at peak of infection seven days after inoculation." (PMID 27662621, 2016). "Within lung parenchyma following infection, IL-17 was produced from CD4+ cells with properties of Th17 cells, as well as γδ T cells." (PMID 27698020, 2016). "We next compared the magnitude and ex vivo characteristics of WNV-specific CD4+ T cell response in subjects with neuroinvasive disease or asymptomatic infection." (PMID 26795118, 2016). "CD4+ T cells produce the same pattern of cytokines more efficiently after a boost infection, likely thanks to the memory response." (PMID 26989699, 2016). "CD4 depletion was maintained: (a) prior to primary infection and continuously throughout the experiment (cont)." (PMID 27242785, 2016). "Dendritic cell DC-SIGN receptor binds to HIV via Env glycans and enables trans-infection of CD4+ T cells, thus facilitating HIV transmission." (PMID 26968525, 2016). "Our previous study found that after infection by H. pylori, the H. pylori antigen induced CD4+ Th1 cells in the gastric mucosa of mice, producing special cellular immunity through antigen-presenting cells." (PMID 26901645, 2016). "A peak of enhanced frequencies of IFNγ-producing CD4+ T cells was detectable on day 7 post infection." (PMID 27875529, 2016). "In that study, it was observed that when HIV infection is performed in a SupT1/PBMC co-culture, the preferential infection of SupT1 cells can spare primary CD4+ T cells from infection and depletion." (PMID 27128948, 2016). "Increased human immunodeficiency virus (HIV) virulence at infection has been suggested by a meta-analysis based on viral load and CD4 T lymphocytes (CD4) count during acute infection." (PMID 26799390, 2016). "Recent studies have shown a high infection rate among CXCR3+ CD4+ T-cells, which are also preferentially enriched for HIV DNA in HIV-infected individuals on cART." (PMID 27509048, 2016).
infection (continued). "The predominant model for establishment of HIV-1 latency entails the infection of an activate CD4 T cell that returns to a resting state, thus removing support for viral transcription." (PMID 26728316, 2016). "The defect in NCM numbers was milder in Csf1ΔCD4 mice than in Csf1ΔUbc mice, indicating that MCSF derived both from CD4+ T cells and T cell-independent sources contributes to expansion of blood monocytes during infection." (PMID 27923070, 2016). "Taken together, these data indicate that LdCen-/- infection in DCs substantially boost the CD4+Th1 cell effector functioning in vitro in both age groups." (PMID 27580076, 2016). "We also found that mice depleted of macrophages and CD4+ T-cells prior to a secondary infection exhibited a significant decrease in the amount of naive CD8+ T-cells at 2 DPI, and this trend remained at 4 DPI." (PMID 27242785, 2016). "In order to corroborate these findings, we utilized our in vivo depletion regimen and isolated splenic CD4+ T cells from mock treated, scramble treated and miR-182 inhibitor treated mice at day 12 post Cm infection." (PMID 27556515, 2016). "These experiments confirmed that interactions of JNK, integrase and Pin1 are likely similar following infection of resting and activated CD4+ T cells and are critical for HIV infection." (PMID 27459960, 2016). "In this model, resting CD4+ T cells 5 day post infection represent a stable latently infected population that respond to latency-reversing agents (LRA) in a similar pattern to CD4+ T cells from HIV-infected individuals on cART." (PMID 27459960, 2016). "Both the frequency and MFI of PD-1 expression in splenic and mesenteric CD4+ T cells showed a continuous increase after infection." (PMID 27792733, 2016). "On the other hand, as it is known that eosinophils can act directly as antigen‐presenting cells after infection with the helminth Strongyloides41, 42, 43, it is possible that eosinophils aid priming CD4+ cell responses." (PMID 26679416, 2016). "CD103+ DCs migrate to the DLN within 2–4 days following infection where they efficiently activate both CD4 and CD8 naïve and memory T cells that recognize viral antigens." (PMID 26965109, 2016). "In Lb+Py group, CD4+SP thymocytes increased 10 days post infection, and returned to control values by day 25th post infection." (PMID 27446022, 2016). "HIV attachment to the host cell via any of these factors likelybrings Env into close proximity with the host receptor CD4 and subsequently one ofthe coreceptors, thus increasing the efficiency of infection." (PMID 28357381, 2016). "Our result also showed M. tb H37Ra infection increases the number of CD4+CD25+ T cells compared to uninfected control." (PMID 27489303, 2016). "We collected from the IEDB 210 CD8+ and 816 CD4+ T cell influenza A-specific epitopes, of length 8–18 residues, known to be targeted during natural infection." (PMID 27402904, 2016). "Productive infection of activated CD4 + T cells induces apoptosis, mediated by activation of both a DNA-dependent protein kinase (DNA-PK) and caspase-3." (PMID 27211546, 2016). "As mice were protected against ivag challenge infection by CD4+ T cells, we sought to define T cell responses in these animals." (PMID 27606424, 2016). "Nonetheless, our data in this specific cohort indicates that CD4 T cell responses and neutralizing antibody titers were linked in SUDV survivors in this window of time, even a decade post infection." (PMID 27187443, 2016). "Not only were Th1 cells and CD4+ CTLs transcriptionally separable, but they were also induced to different degrees in response to different infections." (PMID 27806296, 2016). "This argues for a dynamic CD4+ T-cell compartment in the skin, with an equilibrium set-point that is altered by a history of infection and inflammation." (PMID 27160938, 2016). "In most of these infections, CD4 CTL were important effector cells and, in some cases, responsible for vaccination-induced protection against infection." (PMID 27014272, 2016).
infection (continued). "Together, TSC1f/f LysM-Cre+ mice were able to temporarily contain M. tuberculosis H37Rv infection at the time of recruitment of M. tuberculosis specific CD4+ T cells to the site of infection, possibly due to enhanced autophagy." (PMID 27387347, 2016). "A reduction in Tr1 (CD4+FOXP3-PD1hiIL10+) cells was also observed at three weeks post infection, closely mirroring the predicted 50% reduction at that time." (PMID 27936058, 2016). "Our results on regulation of SR T cells during persistence also corroborated control of transferred SR CD4+ T cell proliferation by Foxp3+ Tregs during a heterologous MHV infection." (PMID 27708643, 2016). "Since IFN-γ is the key cytokine involved in adaptive immunity against Cm infection, and is produced by Ag-specific CD4+ T cells from Cm infected or vaccinated mice, we determined the contribution of miR-182 in generation of Ag-specific IFN-γ." (PMID 27556515, 2016). "The segregation of related proviral and episomal viral sequences at different CD4+ T-cell subsets, as observed in episomal clusters 2 and 3, indicates the occurrence of cross-infection events between them." (PMID 27484989, 2016). "This study was motivated by increasing reports of HIV interaction with erythrocytes and the potential for their surface molecules in mediating the infection of CD4+ cells." (PMID 26900853, 2016). "Given the acute status of the infection in these patients (all of them had CB > 0.3 mg/dL), these data are consistent with the in vitro results: CB modulates the proportion of CD4+CD25+TIM-1+ T cells, even in the presence of the virus." (PMID 27578921, 2016). "The GI tract is an important site of HIV transmission and CD4+ T cell depletion particularly early after infection." (PMID 27438728, 2016). "Co-expression of IFN-γ/TNF-α/TGF-β was significantly affected by METH in the CD4 T cell subpopulation that was very dramatic at the last time point (day 56) of infection." (PMID 27760221, 2016). "Latently infected T-cells were prepared by infection of naïve CD4+ T-cells with HIV-1 NL4-3 followed by culture with IL-7/TGFβ-1 for 2 weeks, a condition modified based upon previous publications." (PMID 27049645, 2016). "Similar to MDV, the infection of human CD4+ T cells by human T cell leukaemia virus type 1 (HTLV-1) is increased in activated CD4+ T cells." (PMID 27894330, 2016). "This cytokine is produced by NKT and NK cells early during infection, followed by CD4+ and CD8+ T cells when the adaptive immune response develops." (PMID 27891126, 2016). "A case for persistent immune activation was observed after successful treatment of HSV-2 with Acyclovir, where increased expression of mucosal CCR5+ CD4+ T-cells remained at the sight of herpetic ulcers long after infection had been cleared." (PMID 27446076, 2016). "Clearance of ivag challenge infection was mediated by interferon (IFN)-γ-producing CD4+ T cells, while IFN-γ signaling blockade concomitant with a single ivag challenge promoted tissue damage by enhancing Chlamydia-specific TH17 immunity." (PMID 27606424, 2016). "We confirmed our findings in vivo using a humanized mouse model, and we observed reduced bystander pathogenesis of the mutant R3A-5/6AA compared to the wild type R3A infection in CD4 T cells in the blood, spleen and bone marrow." (PMID 27026376, 2016). "We found that, similarly to IFN-γ−/− mice, CD4 depletion had minimal impact on overall immune cell infiltration during infection in all mouse strains tested, with the exception of an increase in CD8+ T cell levels at day 21 postinfection." (PMID 27600502, 2016). "In conclusion, our results show that polymorphisms in the gp41CT of subtype C decrease viral infectivity and cell-to-cell transmission, thereby impairing viral propagative infection in CD4+ T-cells, most likely by enabling less Env incorporation into virions." (PMID 27598717, 2016).
infection (continued). "Its production by CD4(+) T-cells is also important for parasite maintenance, even following a clinical cure of infection, and represents a pivotal key for developing adaptive immunity against the parasite." (PMID 27051668, 2016). "To confirm these results in a quantitative manner, we simulate these CD8+ T cell depletion experiments in our most realistic three-stage model, where we allow most CD4+ T cells to die from abortive infection." (PMID 27226367, 2016). "The infection in PLHIV has been associated with the degree of immunosuppression, being more frequent with low CD4 count like in our two patients." (PMID 27646953, 2016). "Mice were infected with P. murina and groups of mice were depleted of CD4+ T-cells and macrophages every 6 days with depletion occurring prior to secondary infection (2°)." (PMID 27242785, 2016). "We have also previously shown that central memory CD4+Th1 cells generated in E. muris-infected mice expand and differentiate into effector memory CD4+Th1 cells following a second IOE infection." (PMID 27092553, 2016). "Other LNG-pelleted mice received agonist anti-CD40 antibody 1 day after infection, while other placebo-pelleted mice received CD4+ cell-depleting mAb 1 day prior to infection and for the duration of the study." (PMID 27892938, 2016). "The activation but poor cytokine production of CD4+ RTEs during infection also displays some hallmarks of bystander activation." (PMID 27658046, 2016). "Such agonists would have the added advantages that they induce a potent block to the replication of HIV-1 in myeloid cells and induce the production of type-I IFN that protects CD4 T cells from infection." (PMID 27905985, 2016). "The enhanced Env: CD4 interactions detected for several Env mutants would be expected to increased their capacity to mediated macrophage infection." (PMID 27820858, 2016). "In fact, the bacteria were efficiently eliminated from the CNS in those CD4+ T cell recipients that succumbed to the infection." (PMID 27875529, 2016). "The establishment of latency in vitro through direct infection of resting CD4+ T-cells is significantly enhanced by CCL19 and mDC, but the efficiency is dependent on virus titre, co-receptor usage and there is significant donor variability." (PMID 27383184, 2016). "Diversification in the pol region over 12 months was greater for men with acute or recent infection, higher CD4 cell count, and lower HIV viral load at study enrollment." (PMID 27936098, 2016). "La infection showed a higher number of the IL-4-producing CD4+ T lymphocyte subset than Lb infection at 4 weeks PI; however, at 8 weeks PI, La infection showed a lower number of IL-4-producing CD4+ T-cells than Lb infection." (PMID 27073297, 2016). "Addition of the TLR2 agonist zymosan to M. smegmatis cultures prior to PBMC infection increased HIV infectivity of isolated CD4+ T cells 6.2-fold relative to untreated M. smegmatis cultures (p<0.01)." (PMID 26807859, 2016). "HIV pol diversification was more pronounced in men with acute or recent infection, higher CD4 cell count, and lower HIV viral load." (PMID 27936098, 2016). "During the course of an immune response, CD4+ T helper cells identify invading pathogens, proliferate and secrete cytokines to aid in immune-mediated clearance of infection." (PMID 26743592, 2016). "Eomesodermin (Eomes), a key transcription factor associated with the cytolytic activity of CD4+ T cells was expressed at similar levels by CD38+ and CD38- CD4+ T cells prior to infection." (PMID 27662621, 2016). "In these experiments, three experienced scientists performed these experiments using multiple different donors and each found similar results–that roughly half of the donors required the presence of CCL19 to facilitate infection of resting CD4+ T-cells." (PMID 27383184, 2016).